SETDB2 (SET domain bifurcated histone lysine methyltransferase 2)
Description:
Histone methyltransferase involved in left-right axis specification in early development and mitosis. Specifically trimethylates 'Lys-9' of histone H3 (H3K9me3). H3K9me3 is a specific tag for epigenetic transcriptional repression that recruits HP1 (CBX1, CBX3 and/or CBX5) proteins to methylated histones. Contributes to H3K9me3 in both the interspersed repetitive elements and centromere-associated repeats. Plays a role in chromosome condensation and segregation during mitosis.
Synonyms: C13orf4; CLLD8; KMT1F; CLLL8
Tractability: Small molecule: a structure with a bound ligand is known. PROTAC: ubiquitination databases record sites on it.
Gene: Protein-coding gene on chromosome 13 (49,443,794 to 49,495,003, forward strand). Ensembl gene ENSG00000136169.
Subcellular location: Nucleus; Chromosome
Subcellular location (Human Protein Atlas): Nucleoplasm; Cytosol
Pathways (Reactome):
Chromatin organization: PKMTs methylate histone lysines
Gene Ontology:
Molecular function: histone H3K9 methyltransferase activity; protein binding; histone H3 methyltransferase activity; DNA binding; histone H3K9me2 methyltransferase activity; histone methyltransferase activity; zinc ion binding
Biological process: chromosome segregation; mitotic cell cycle; heart looping; heterochromatin organization; left/right axis specification; negative regulation of DNA-templated transcription; negative regulation of gene expression; chromatin remodeling
Cellular component: nucleoplasm; nucleus; chromosome
Genetic constraint (gnomAD): Loss-of-function variants: 38 observed, 58.04 expected, observed/expected ratio (o/e) 0.65, 90% interval 0.5 to 0.86. The upper end of that interval is the gene's LOEUF score, 0.86, which puts it in group 3 of 6, group 1 being the genes least tolerant of losing a copy. Missense variants: 530 observed, 668.31 expected, observed/expected ratio (o/e) 0.79, 90% interval 0.74 to 0.85. Synonymous variants: 212 observed, 243.81 expected, observed/expected ratio (o/e) 0.87, 90% interval 0.78 to 0.97.
Homologues: Orthologues: chimpanzee SETDB2 (99% identical), macaque SETDB2 (97% identical), dog SETDB2 (81% identical), pig SETDB2 (81% identical), rabbit SETDB2 (80% identical), guinea pig SETDB2 (68% identical), rat LOC134482125 (68% identical), mouse Setdb2 (67% identical), tropical clawed frog setdb2 (36% identical), Drosophila melanogaster egg (23% identical), Caenorhabditis elegans met-2 (16% identical), Drosophila melanogaster G9a (15% identical), and 15 more. Paralogues in human: SETDB1 (32% identical), EHMT1 (18% identical), EHMT2 (18% identical), ASH1L (14% identical), KMT2C (13% identical), KMT2D (13% identical), KMT2A (13% identical), SUV39H1 (13% identical), SUV39H2 (12% identical), KMT2B (12% identical), NSD1 (12% identical), NSD2 (11% identical), and 7 more.
Diseases named in the same sentence as SETDB2 in open-access papers:
SETDB2 is named in the same sentence as 43 diseases in open-access papers, as found by Europe PMC text mining. Sharing a sentence is not in itself a finding about the gene and the disease. The quoted sentences say what the papers report.
gastric cancer (6 papers, 2016 to 2023). A primary or metastatic malignant neoplasm involving the stomach. "A recent review reported that low expression of SETDB2 was associated with shorter disease-free survival time in renal cell tumors, while in gastric cancer, SETDB2 overexpression predicted poor prognoses and was associated with tumor progression." (PMID 36263018, 2022). "In cancer research, SETDB2 has been found to be involved in cell cycle dysregulation in acute leukemia 20, associated with the prognosis and metastasis of renal tumors 21, and plays an oncogenic role in gastric cancer." (PMID 32549764, 2020). "Different from oncogenic roles in breast cancer, gastric cancer, or leukemia, we identified that SETDB2 is a tumor repressor in LUAD, which expressed lowly in tumor samples." (PMID 36504353, 2023). "SETDB2 is a histone H3 lysine 9 (H3K9) trimethyltransferase, and its overexpression is associated with poor prognosis of gastric cancer patients." (PMID 36457486, 2022). "The histone H3K9 methyltransferase SETDB2 is involved in cell cycle dysregulation in acute leukemia and has oncogenic roles in gastric cancer." (PMID 32549764, 2020). "There is less information about the involvement of SETDB2 in cancer; however it was recently reported that SETDB2 overexpression in gastric cancer patients correlating with late stage and poor prognosis." (PMID 28587163, 2017). "The same group, using human gastric cancer cells in vitro, demonstrated that SETDB2 knockdown and overexpression significantly decreased and increased cell proliferation, migration and invasion, respectively, accompanied with the expected global changes in H3K9me3 levels." (PMID 28587163, 2017). "Since it is still unknown whether SETDB2 is linked to carcinogenesis, we studied alterations and functions of SETDB2 in human gastric cancers (GCs)." (PMID 27572307, 2016). "Thus, SETDB2 expression and function detected in our study were similar to those of SETDB1 and SUV39H1 in cancers, suggesting that SETDB2 may have oncogenic functions and overexpression of SETDB2 play roles in gastric cancer progression." (PMID 27572307, 2016).
breast carcinoma (5 papers, 2015 to 2024). "Restoring SETDB2 expression reversed the loss of breast cancer stem cell maintenance observed upon SETDB2-knockdown." (PMID 32549764, 2020). "We found that copy number amp/gain of NSD1 or PRDM1, or loss of SETDB2 or PRDM10 was significantly associated (p<0.05) with shorter survival in breast cancer patients." (PMID 25537518, 2015). "First, we overexpressed SETDB2 wildtype and SETDB2 2GA mutation in MCF7 breast cancer cells, and examined histone methyltransferase activity through H3K9me3 immunofluorescence staining." (PMID 38151757, 2024). "In SETDB2 wildtype overexpression MCF7 breast cancer cells, the H3K9me3 staining signal significantly increased, while the H3K9me3 staining signal in vector and SETDB2 2GA mutation groups did not change." (PMID 38151757, 2024). "In order to confirm the function of SETDB2 in cell mitotic progression, we knocked down SETDB2 in SUM159PT breast cancer cells." (PMID 38151757, 2024). "In conclusion, our study reveals a novel function of SETDB2 in cancer stem cell maintenance in breast cancer." (PMID 32549764, 2020). "In our study, we found that the SETDB2 expression level was significantly increased in mammospheres of breast cancer cells." (PMID 32549764, 2020). "First, we found that the SETDB2 expression level was significantly increased in mammospheres derived from breast cancer cell lines." (PMID 32549764, 2020). "Depleted SETDB2 significantly decreased the breast cancer stem cell population and mammosphere formation in vitro and also inhibited breast tumor initiation and growth in vivo." (PMID 32549764, 2020). "Restoring ΔNp63α expression in SETDB2-knockdown breast cancer cells rescued the breast cancer stem cell maintenance." (PMID 32549764, 2020). "To explore the potential function of SETDB2 in breast cancer, we examined SETDB2 function in tumor growth in vivo." (PMID 32549764, 2020). "To study the function of SETDB2 in BCSCs, we examined the protein levels of SETDB2 in several breast cancer cell lines and found that SETDB2 was expressed in most breast cancer cell lines." (PMID 32549764, 2020). "Restoring ΔNp63α expression rescued the breast cancer stem cell maintenance defect which mediated by SETDB2 knockdown." (PMID 32549764, 2020). "Restoring ΔNp63α expression rescued the breast cancer stem cell maintenance defect mediated by SETDB2-knockdown." (PMID 32549764, 2020). "Next, we performed quantitative RT-PCR (qRT-PCR) analysis to measure the mRNA expression level of eight HMTs (SETDB1, ASH1L, SMYD2, SMYD3, SETD1A, WHSC1L1, SUV420H1, and SETDB2) in 20 breast cancer cell lines." (PMID 25537518, 2015). "Breast cancer cell lines with deletion of SETDB2, such as SUM229, SUM149, HCC170, and SUM190, showed dramatically lower mRNA levels than MCF10A cells." (PMID 25537518, 2015). "We found that for seven HMTs (KMT2C, SETDB2, SETD2, SETMAR, PRDM1, PRDM5, and PRDM8), copy number amp/gain or deletion was significantly associated (p<0.05) with shorter survival in breast cancer patients." (PMID 25537518, 2015). "In a mouse model, silencing of SETDB2 also decreased breast cancer initiation and tumor growth." (PMID 32549764, 2020). "In our study, we discovered a novel function of SETDB2 in breast cancer stem cell maintenance." (PMID 32549764, 2020). "In our study, we found that SETDB2 plays essential roles in breast cancer stem cell maintenance." (PMID 32549764, 2020). "Thus, all these data indicated that SETDB2 interacts with ΔNp63α, methylates and stabilizes ΔNp63α protein for breast cancer stem cell maintenance." (PMID 32549764, 2020). "Our study reveals a novel function of SETDB2 in breast cancer stem cells." (PMID 32549764, 2020). "In conclusion, SETDB2 interacts with ΔNp63α, methylates and stabilizes ΔNp63α to upregulate the transcription of the Hedgehog signaling pathway-associated genes CXCR4, PTCH1 and GLI2, which promote breast cancer stem cell maintenance and tumor initiation." (PMID 32549764, 2020).
breast carcinoma (continued). "To further confirm whether SETDB2 promoted breast cancer stem cell maintenance by ΔNp63α, we restored ΔNp63α expression in MDA-MB-231 SETDB2-knockdown cells." (PMID 32549764, 2020). "Restoring SETDB2 expression rescued the defect in breast cancer stem cell maintenance." (PMID 32549764, 2020). "SETDB2-knockdown showed less of an effect on the proliferation of breast cancer cells." (PMID 32549764, 2020). "Two HMT genes, PRDM7 and SETDB2, showed homozygous deletion in more than 2% of breast cancers." (PMID 25537518, 2015). "In addition, consistent with our findings in primary breast cancers, we also found that other HMTs, such as WHSC1L1, SUV420H1, and SETD1A, were commonly gained or amplified, and SETDB2 was commonly lost or deleted in breast cancer cell lines." (PMID 25537518, 2015). "Thus, our study reveals an essential function of SETDB2 in breast cancer stem cell maintenance." (PMID 32549764, 2020). "Thus, our study reveals a novel role of SETDB2 in breast cancer stem cell maintenance." (PMID 32549764, 2020). "Of the two most common HMTs with homozygous deletions, SETDB2 exhibited the highest frequency of homozygous deletion (6.82%) in basal-like samples, and PRDM7 was most frequent (5.79%) in Luminal B breast cancer." (PMID 25537518, 2015). "We found that SETDB2 knockdown significantly increased the percentage of abnormal nuclei in SUM159PT breast cancer cells, abnormal spindle and chromosome segregation in metaphase and anaphase of mitosis, and G2/M arrested cells in SUM159PT breast cancer cells." (PMID 38151757, 2024). "In addition, we also found that SETDB2 knockdown diminished the interaction between CDC20 and BUBR1 or APC3 (APC/C complex component protein) in MCF7 breast cancer cells." (PMID 38151757, 2024). "Previous studies have indicated that SETDB2 could interact with and stabilize ΔNp63α to promote cancer stem cell (CSC) maintenance in breast cancer." (PMID 36504353, 2023). "However, the roles and mechanism of SETDB2 in cancer stem cells and breast cancer are not clear." (PMID 32549764, 2020). "Immunoprecipitation showed that SETDB2 endogenously interacted with BUBR1 rather than MPS1, CDC20, or MAD2 in MCF7, MDA‐MB‐231, and SUM159PT breast cancer cells." (PMID 38151757, 2024).
atherosclerosis (4 papers, 2021 to 2025). A disease characterized by the build-up of fatty material and calcium deposition in the arterial wall resulting in partial or complete occlusion of the arterial lumen. "This suggests Setdb2 is involved with chronic inflammation associated with metabolic disorders such as atherosclerosis." (PMID 40502770, 2025). "We further show that deficiency of SETDB2 in hematopoietic cells promoted the progression of atherosclerosis and plaque instability in atherosclerotic mice." (PMID 34003795, 2021). "Genes upregulated in Setdb2-deficient samples were enriched in cell apoptosis and atherosclerosis signaling, whereas downregulated ones were associated with impaired regulation of anti-inflammatory response." (PMID 34708045, 2021). "Together, these findings demonstrate that loss of Setdb2 in hematopoietic cells accelerates the progression of atherosclerosis and promotes plaque instability by increasing inflammation and macrophage accumulation in the lesions." (PMID 34003795, 2021). "Hematopoietic SETDB2 deficiency promotes the progression of atherosclerosis." (PMID 34003795, 2021). "Overall, the major finding of this study is the identification of SETDB2 as a major regulator of immune activation during atherosclerosis." (PMID 34003795, 2021). "In summary, we identified SETDB2 as an important regulator of macrophage function and inflammatory response during atherosclerosis." (PMID 34003795, 2021). "To determine the in vivo function of SETDB2 during the progression of atherosclerosis, we developed mice with a gene trap insertion at the Setdb2 locus that is designed to limit global expression of the Setdb2 gene (Setdb2GT mice)." (PMID 34003795, 2021). "Upregulation of histone lysine methyltransferase SETDB2, a member of the KMT1 family, was observed in proinflammatory M1, whereas deficiency of SETDB2 in hematopoietic cells promoted vascular inflammation and accelerated atherosclerosis." (PMID 38031118, 2023). "Together, the functional relevance of SETDB2 in inflammation, immunity and lipid metabolism suggest that SETDB2 might regulate atherosclerosis." (PMID 34003795, 2021). "Further studies will be needed to assess the nonenzymatic function of SETDB2 in regulating macrophage functions during atherosclerosis." (PMID 34003795, 2021).
influenza (4 papers, 2017 to 2025). An acute viral infection of the respiratory tract, occurring in isolated cases, in epidemics, or in pandemics; it is caused by serologically different strains of viruses (influenzaviruses) designated A, B, and C, has a 3-day incubation period, and usually lasts for 3 to 10 days. "Very recent studies have also highlighted a still incompletely understood process in which influenza infection causes type-I interferon-induced upregulation of the lysine methyltransferase Setdb2, and the subsequent silencing of antiviral effectors in macrophage by H3K9me3 formation." (PMID 28257484, 2017). "In influenza infection, Setdb2 did the same at the Cxcl1 gene, reducing neutrophil-driven inflammation." (PMID 40948770, 2025). "Previous work examining SETDB2 in influenza and wound repair has found that SETDB2 is dependent on JAK/STAT signaling." (PMID 34479991, 2021). "Although the role of SETDB2 in Mφs in response to coronavirus is unknown, during influenza infection, up-regulation of SETDB2 dampens inflammation leading to enhanced susceptibility to bacterial superinfections." (PMID 34479991, 2021).
lung adenocarcinoma (4 papers, 2023 to 2024). A carcinoma that arises from the lung and is characterized by the presence of malignant glandular epithelial cells. "At the same time, we analyzed the mutation rates of H3K36 enzymes (including NSD1, NSD2, NSD3, ASH1L, SMYD2, SETDB2, SETD3, and SETMAR) in lung adenocarcinoma, which showed that the amplification mutation frequency of H3K36 enzymes was at a low level." (PMID 39119928, 2024). "We queried the expression levels of SETDB2 in the Cancer Cell Line Encyclopedia (CCLE) dataset and selected three human lung adenocarcinoma cell lines (A549, H1299, and H522) to conduct the experimental assays." (PMID 36504353, 2023).
diabetes (3 papers, 2023 to 2025). "Another study has shown that SETDB2 expression in wound macrophages is upregulated by IFN-β, whereas the IFN-β -SETDB2 axis is impaired in diabetes, leading to a persistent inflammatory macrophage phenotype." (PMID 37428812, 2023). "In diabetes, we showed that TNF-α signaling was increased in wound fibroblasts, which functions to increase Setdb2 expression and represses fibroblast to myofibroblast transition." (PMID 41277557, 2025).
acute lymphoblastic leukemia (2 papers, 2021 to 2023). Leukemia with an acute onset, characterized by the presence of lymphoblasts in the bone marrow and the peripheral blood. "In addition, SETDB2 inhibition promotes the sensitivity to kinase inhibitors in acute lymphoblastic leukemia (ALL), suggesting a rational target for treatment." (PMID 36504353, 2023). "Notably, SETDB2 has been reported to be involved in the regulation of cell cycle progression in acute lymphoblastic leukemia but does not have any effect on normal hematopoietic stem and progenitor cell proliferation." (PMID 34003795, 2021).
asthma (2 papers, 2015 to 2023). "Future work will need to focus on the functions of PHF11 and SETDB2 in asthma pathophysiology, in particular, how the two molecules work together during immune cell regulation." (PMID 26378653, 2015). "Therefore, SETDB2 dysregulation is associated with genomic instability and increased H3K9 methylation, leading to Th1/Th2 cell imbalance and asthma onset." (PMID 37569643, 2023). "In addition, SETDB1 interacts with the asthma-related gene SETDB2; the latter antagonizes the KDM4C gene to control H3K9 methylation, which affects the expression of ORMDL3, a well-known asthma-related gene." (PMID 37569643, 2023).
co-infection (2 papers, 2018 to 2024). "Therefore, the elevated expression of the SETDB2 gene indicated by our results, as well as the increased H3K9 methylation, suggests that, during co-infection with TB-HIV, there is significant transcriptional silencing." (PMID 38792830, 2024).
HIV-1 infection (2 papers, 2015 to 2019). The type species of lentivirus and the etiologic agent of acquired immunodeficiency syndrome (AIDS). "Among the up-regulated genes detected after HIV-1 infection, the gene encoding for SETDB2 protein had the most up-regulated expression." (PMID 25875202, 2015). "For example, Setdb2 and Prmt6 were involved in defense against Influenza A virus and HIV-1 infection." (PMID 31057555, 2019). "Altogether, these data show increased expression of RSK2 and SETDB2 at transcriptional and translational levels in host cells after HIV-1 infection." (PMID 25875202, 2015). "Thus, SETDB2 up-regulation could be considered an earlier marker of the HIV-1 infection in host cells." (PMID 25875202, 2015). "Our results indicated that in infected cells, mainly at 24 hours after HIV-1 infection, the expression of SETDB2 is up-regulated in either activated or non-activated cells, indicating that HIV-1 infection could be correlated with the expression of this gene." (PMID 25875202, 2015).